FANCC (FA complementation group C)
Diseases named in the same sentence as FANCC in open-access papers (continued):
Sharing a sentence is not in itself a finding about the gene and the disease.
breast carcinoma (continued). "Since FANCC deleterious mutations existed in Chinese high-risk breast cancer patients according to our data, genetic counseling for breast cancer shall also include FANCC deleterious mutations, though further investigations on the penetrance and spectrum of FANCC mutations are highly warranted." (PMID 30967997, 2019). "The frequency of FANCC mutations in high-risk breast cancer patients has been under-investigated." (PMID 30967997, 2019). "Moreover, grandmothers who were FANCC mutation carriers had the highest risk of breast cancer (SIR: 2.4; 95% CI: 1.1–5.2)." (PMID 30967997, 2019). "However, the role of the FA genes most commonly mutated, FANCA and FANCC, in the risk of developing breast cancer has remained uncertain." (PMID 31467304, 2019). "Investigations on the germline mutation of FANCC in high-risk breast cancer patients are sparse." (PMID 30967997, 2019). "It is also possible that the two prototype FANCC truncating variants analysed here, despite being FA-causing, have reduced penetrance for breast cancer due to some residual function, and other particular FANCC variants may confer a more substantial risk." (PMID 31467304, 2019). "However, variants in two candidate genes, PRSS50 and FANCC, were prioritised as top candidates for the accessory breast phenotype in the family because these two genes have previously been implicated in breast diseases such as breast cancer." (PMID 41296379, 2025). "Homozygous mutations in FANCC are responsible for FA complementation group C. FANCC is a breast cancer suppressor." (PMID 30967997, 2019). "The patient with FANCC c.51G>C mutation was diagnosed with triple-negative (ER-, PR- and HER2-) breast cancer at the age of 41 years." (PMID 30967997, 2019). "PALB2 is an established breast cancer susceptibility gene, and the investigated mutation p.R414X25 occurred at a similar frequency to the tested FANCC mutations." (PMID 31467304, 2019). "Poor survival in breast cancer patients with alternative FANCC genes suggested that FANCC is a breast cancer suppressor." (PMID 30967997, 2019). "Their penetrance is unknown, however, the difficulties to confirm very early reports of an increased breast cancer risk in obligate heterozygotes from FA families may indicate that the risks are genetically heterogeneous and moderate on average, with a possible preponderance of FANCC." (PMID 24025454, 2013). "FANCC c.339G>A (W113X) was classified as pathogenic/likely pathogenic in ClinVar database while it was not reported in breast cancer patient." (PMID 30967997, 2019). "The FANCC variants among familial breast and/or ovarian cancer patients (n = 255), sporadic breast cancer patients (n = 250) and female non-cancer controls (n = 248)." (PMID 30967997, 2019). "The first study investigating FANCC germline mutations enrolled 88 BRCA1/2-negative familial breast cancer patients from the United Kingdom, finding no deleterious mutations by conformation sensitive gel electrophoresis followed by a sequencing assay." (PMID 30967997, 2019). "While truncating variants in BRCA2 and PALB2 confer a substantial risk of breast cancer, our study suggests that truncating FANCC variants do not confer a comparable risk." (PMID 31467304, 2019). "No overall increased risk of breast cancer was seen in our study but the number of families with FANCC mutations would have been small as this group accounts for less than 10% of non-Ashkenazi Jewish FA cases." (PMID 18786261, 2008). "A previous study of familial breast cancer cases did not identify mutations in FANCA, C, D2, E, F, G, so at present it remains unclear whether FANCC, which acts upstream of FANCD2, is a breast cancer predisposing gene." (PMID 18786261, 2008).
breast carcinoma (continued). "However, another study which recruited 42 Ashkenazi Jewish women who were FANCC heterozygous carriers showed that the risk of breast cancer was not significantly elevated in the carriers (both 2.2% for the carriers and controls)." (PMID 30967997, 2019). "A previous sequencing study of Australian multiple-case breast cancer families had identified truncating variants in FANCC in 3 of 438 multiple-case breast cancer families but in none of 464 healthy controls, suggestive of a predisposing role for FANCC variants in breast cancer." (PMID 31467304, 2019). "Recently, three studies which were conducted in the United States, Russia, and China used gene panel sequencing to screen the multi-gene germline mutations in high-risk BRCA1/2-negative breast cancer patients, yet none of the FANCC germline mutations were found." (PMID 30967997, 2019). "Two missense variations in FANCC and FANCG genes, predicted to be deleterious, were further identified in breast cancer cases with family history of different tumors including leukemia, breast, prostate, and colon cancers." (PMID 38313678, 2024). "Deletion analysis of PHF2, FANCC, PTCH1 and XPA were examined in a subset of 47 early-onset (group-A: ≤ 40 years) and 59 late-onset (group-B: > 40 years) breast carcinomas using both microsatellite and exonic markers." (PMID 18990233, 2008). "We thus profiled metabolites in the MDA-MB-321 breast cancer cells with and without ectopically- expressed FANCC." (PMID 29930218, 2018). "Although the concept of increased cancer risk conferred by heterozygous mutations now seems unassailable, the evidence for specific associations between FANCC and BLM and breast cancer risk is not yet convincing." (PMID 23028381, 2012). "We further screened these samples for hypermethylation of the FANCC promoter region and for lack of FANCC mRNA expression, as epigenetic FANCC inactivation has previously been reported in acute leukaemia and breast cancer." (PMID 20509860, 2010). "Moreover, IHC analysis showed that FANCC was negative in the breast cancer tissue of this patient." (PMID 30967997, 2019).
anemia (12 papers, 2010 to 2026). A reduction in the number of red blood cells, the amount of hemoglobin, and/or the volume of packed red blood cells. "In this study, we found that the Fanconi anemia protein, FANCC interacts directly with the microtubule-associated protein STMN1, involved in microtubule dynamics during cellular division." (PMID 26466335, 2015). "FANCC is the cytoplasmic component of the FA pathway, and in association with the Fanconi anemia group E (FANCE) protein, translocates to the nucleus in response to crosslink damage." (PMID 24676280, 2014). "BRCA2, Fanconi anemia complementation group protein C (FANCC) and a combination of FANCC and Fanconi anemia complementation group protein G (FANCG) mutations have been found in pancreatic cancer patients." (PMID 28471392, 2017). "The panel included retinoblastoma binding protein 9 (RBBP9), Caspase recruitment domain family 11 (CARD11), Fanconi anemia complementation group c (FANCC), double minute 4 (MDM4), and breast cancer 1 (BRCA1)." (PMID 22859999, 2012).
pancreatic cancer (10 papers, 2010 to 2025). "FANCC is less well characterized and associated with lower penetrance for hereditary cancer risk; limited research suggests an association with pancreatic cancer." (PMID 32793315, 2020). "Screening of germline DNA in 421 pancreatic cancer cases showed that, besides homozygote-associated cancer formation, heterozygous FANCC mutations were associated with increased susceptibility to pancreatic cancer." (PMID 26596371, 2015). "In particular, germline mutations of FANCC have been described in pancreatic cancer, associated with LOH in the tumor." (PMID 20509860, 2010). "In comparison, genetic inactivation of the proximal FA pathway appears to occur infrequently in tumors among the general population and has, in terms of GI cancers, yet only been reported in pancreatic cancer, where it was associated with rare mutations in FANCC or FANCG." (PMID 20509860, 2010). "In addition, germline mutations of FANCC might contribute to the tumorigenesis or tumor progression of pancreatic cancer." (PMID 20509860, 2010). "Pancreatic cancer showed an exceptionally high biallelic loss in HRR genes, with BRCA1, CDK12, FANCC, PPP2R2 A, RAD51 C, RAD51D, RAD52, WRN, and XRCC3 all presenting 100% biallelic loss." (PMID 40420266, 2025). "Furthermore, we tested the impact of EXO1 KO in the patient-derived FANCC-deficient pancreatic cancer cell line PL1140, which has a defect in FANCD2 monoubiquitylation that can be restored by complementation with wild-type FANCC." (PMID 41006228, 2025). "The FANCC (located on chromosome 9q) and FANCG (located on chromosome 9p) genes are additional Fanconi complementation group genes which have been implicated in the pathogenesis of pancreatic cancer." (PMID 24624093, 2014). "However, germline and somatic changes in FANCC and FANCG may have comparatively low penetrance for pancreatic cancer, which is supported by studies investigating germline mutations of upstream FA pathway genes in sporadic, yet FA-typical tumors among the general population." (PMID 20509860, 2010).
ovarian carcinoma (9 papers, 2008 to 2025). A malignant neoplasm originating from the surface ovarian epithelium. "Pathogenic and likely pathogenic variants in FANCC were also reported in individuals with breast and ovarian cancer." (PMID 41296379, 2025). "Methods: 255 BRCA1/2-negative Chinese familial breast and/or ovarian cancer (FBOC) patients were recruited for FANCC germline mutations screen." (PMID 30967997, 2019). "Another patient with ovarian cancer also had an FANCC P/LPGV identified on the germline sequencing only; however, the typical cancer phenotypes associated with FANCC variants include head and neck as well as lung squamous cell carcinomas." (PMID 41465149, 2025). "A similar study conducted in a Chinese cohort with familial breast and/or ovarian cancer that lacked BRCA1/2 mutations observed a deleterious variant (c.339G>A, W113X) in FANCC." (PMID 41296379, 2025).
hereditary cancer (4 papers, 2020 to 2022). Malignant neoplasms occurring in families at a rate greater than that expected by chance and caused by germline mutations in a specific gene. "In addition to mutations associated with risk of hereditary cancer, pathogenic/likely pathogenic mutations were detected in ERCC2 (n = 1), FANCA (n = 1), FANCC (n = 1), HNF1A (n = 1), PRF1 (n = 1) RECQL4 (n = 2), WRN (n = 1), and XPA (n = 1)." (PMID 31963545, 2020). "A prospective cohort of 1021 unrelated cancer cases with clinical suspicion of hereditary cancer was screened for mutations in the following 14 FA genes: FANCA, FANCB, FANCC, FANCD2, FANCE, FANCF, FANCG/XRCC9, FANCI, FANCL/PHF9, FANCM, FANCP/SLX4, FANCQ/ERCC4, FANCR/RAD51 and FANCU/XRCC2." (PMID 32235514, 2020).
lung carcinoma (4 papers, 2016 to 2023). "The index carrier of FANCC c.897G>T; p.Arg299Ser from family F1606 reported a mother with OC and a father with lung cancer." (PMID 36969007, 2023).
acute myeloid leukemia (3 papers, 2016 to 2022). Acute myeloid leukemia (AML) is a group of neoplasms arising from precursor cells committed to the myeloid cell-line differentiation. "Concerning the hematologic phenotype, patients with FANCG PV have been found to have more severe cytopenia as well as a higher frequency and an earlier diagnosis of acute myeloid leukemia or myelodysplastic syndrome than patients with FANCA or FANCC genotypes." (PMID 35216452, 2022). "FANCC was methylated in 1 of 143 acute myeloid leukemia (AML) cases and 3 of 97 acute lymphoblastic leukemia (ALL) cases, while FANCL was found to be methylated in one ALL sample." (PMID 26967246, 2016).
bone marrow failure (3 papers, 2010 to 2021). "In addition, under replicative pressure, FANCC promotes short telomere maintenance in the absence of telomerase and its deficiency accelerates telomere attrition in bone marrow cells, potentially participating in the FANCC’s patient bone marrow failure." (PMID 33723374, 2021). "Since others have previously also documented successful HDR gene editing strategies to repair or compensate defects in FANCA, FANCC, FANCD1/BRCA2 and FANCI, the combined data support that gene editing can be a promising therapeutic strategy to prevent onset of bone marrow failure in FA patients." (PMID 30683899, 2019).
colon cancer (3 papers, 2016 to 2024). "Despite the refusal of the father of the patient to undergo genetic testing, his history of colon cancer and the detection of the same FANCC mutation in the patient’s son strongly suggest a genetic component in the development of the malignancies in this patient." (PMID 31484545, 2019). "We are grateful to Dr. Scott Kern for his generous gift of recombinant colon cancer cell lines RKO (FANCC parent), FCH3C12 (FANCC het +/−/−), FCE11C12 (FANCC null (−/−/−), DLD1 (BRCA2 parent), A9.A2 (BRCA2 het +/−) and A10.A3 (BRCA2 null −/−)." (PMID 27616351, 2016).
acute lymphoblastic leukemia (2 papers, 2016 to 2025). Leukemia with an acute onset, characterized by the presence of lymphoblasts in the bone marrow and the peripheral blood. "For instance, high methylation of the FANCF (observed in a leukaemic CHRF-288 cell line), FANCC, and FANCL have been reported in a small portion of primary AML and acute lymphoblastic leukemia (ALL) cases." (PMID 40739565, 2025).
asthma (2 papers, 2018 to 2020). "Finally, in the asthma vs. HC comparison, 9 SNPs were identified, with 2 associated with risk in the MS4A2 gene (rs573790 p = 0.001, OR = 1.70, CI 95% = 1.21-2.37), and 7 SNPs associated with protection in 4 genes (TBXAS1, FANCC, CYSLTR2, and PTGER3)." (PMID 30254660, 2018). "In the last comparison asthma vs. control group we detected seven SNPs in four genes (TBXAS1, FANCC, CYSLTR2, and PTGER3)." (PMID 31936183, 2020). "When comparing asthma vs. CG TBXAS1-rs13239058, FANCC-rs1326188 and OBSCN-rs465344 obtained p < 0.02 in the codominant model, TBXAS1-rs13239058CC had statistical significance in the dominant model p = 0.02, OR = 0.61, FANCC-rs132618AA p = 0.007, OR = 0.48, and OBSCN-rs465344GG p = 0.004, OR = 2.16." (PMID 31936183, 2020).
Bloom syndrome (2 papers, 2012). Bloom syndrome (BSyn) is a rare chromosomal breakage syndrome characterized by a marked genetic instability associated with pre- and postnatal growth retardation, facial sun-sensitive telangiectatic erythema, increased susceptibility to infections, and predisposition to cancer. "Remarkably, two families carried overtly deleterious mutations in the Fanconi anemia (FA) gene FANCC and one family carried an overtly deleterious mutation in the Bloom's syndrome (BS) gene BLM." (PMID 23028381, 2012).
breast neoplasm (2 papers, 2014 to 2025). A benign or malignant neoplasm of the breast parenchyma. "Lastly, loss-of-function (LoF) variants, similar to those observed in FANCC in the current study, have been reported in individuals with breast neoplasms." (PMID 41296379, 2025). "Secondly, FANCC interacts with very important genes such as BRCA1, which is a well-established gene associated with breast neoplasms." (PMID 41296379, 2025).
Ewing sarcoma (2 papers, 2025). A small round cell tumor that lacks morphologic, immunohistochemical, and electron microscopic evidence of neuroectodermal differentiation. "Germline pathogenic variants in DDR genes, including FANCC, CHEK2, and FANCA, have been reported as predisposing to the development of Ewing sarcoma." (PMID 40563612, 2025).
melanoma (2 papers, 2007 to 2016). A malignant, usually aggressive tumor composed of atypical, neoplastic melanocytes. "In addition, databases deposited in NCBI revealed that FANCA, FANCL, and probably FANCC genes were upregulated in E2F1-overexpressed SKMEL-2 melanoma cells." (PMID 19936073, 2007). "In line with a crosstalk between MiTF and the FANC pathway, MiTF silencing in melanoma cells triggered a strong reduction in the mRNA level of 4 analysed FANC genes: FANCA, FANCD2, FANCC and FANCG." (PMID 27827420, 2016).
prostate carcinoma (2 papers, 2020 to 2023). A carcinoma that arises from epithelial cells of the prostate gland. "In several tumor types, particularly breast, ovarian, pancreatic, and prostate cancers, a strong correlation was observed between increased gLOH and biallelic alterations in other HR genes beyond BRCA1 and BRCA2, including BARD1, PALB2, FANCC, RAD51C, and RAD51D." (PMID 37761329, 2023).
Alzheimer disease (1 paper, 2018). A progressive, neurodegenerative disease characterized by loss of function and death of nerve cells in several areas of the brain leading to loss of cognitive function such as memory and language. "Interestingly, the FANCC gene has been associated with entorhinal cortex thickness, a region that is affected early in the progression of Alzheimer’s disease (AD)." (PMID 30213274, 2018).
anal atresia (1 paper, 2025). "In the porcine genome, the FANCC gene correlates significantly with features of developmental anomalies such as anal atresia." (PMID 40805107, 2025).
anaplastic meningioma (1 paper, 2023). A WHO grade III meningioma characterized by the presence of malignant morphologic features, including malignant cytology and a very high mitotic index (20 or more mitoses per ten high power fields). "Additionally patient #2 suffered from anaplastic meningioma CNS WHO grade 3 with BAP1 mutation, FANCC mutation and homozygous CDKN2A/B deletion in both manifestations." (PMID 36641486, 2023).
breast diseases (1 paper, 2025). "Firstly, PRSS50 has not been previously reported to be associated with hereditary breast diseases, as is the case for FANCC." (PMID 41296379, 2025). "Pathogenic variants in the PRSS50 and FANCC genes have been implicated in breast disease." (PMID 41296379, 2025). "Among these, PRSS50 and FANCC emerged as top candidates, being implicated in breast diseases." (PMID 41296379, 2025). "Aside from PRSS50 and FANCC, numerous other aetiologic variants in 10 genes were found to segregate with the accessory breast phenotype in the family, even though these genes have not been previously linked to breast diseases." (PMID 41296379, 2025).
central nervous system infection (1 paper, 2021). "However, it is not known whether FANCC binds to the nucleocapsid or tegument proteins of HSV-1, whereas an in vivo study verified that FANCC-deficient mice are more susceptible to lethal central nervous system infection by HSV-1, compared to wild-type mice." (PMID 34062931, 2021).